LINC00703 (long independently transcribed non-coding RNA 703)
Gene: Long non-coding RNA gene on chromosome 10 (4,382,211 to 4,410,809, forward strand). Ensembl gene ENSG00000224382.
Diseases named in the same sentence as LINC00703 in open-access papers:
LINC00703 is named in the same sentence as 1 disease in open-access papers, as found by Europe PMC text mining. Sharing a sentence is not in itself a finding about the gene and the disease. The quoted sentences say what the papers report.
hepatocellular carcinoma (1 paper, 2021). A malignant tumor that arises from hepatocytes. "For instance, LINC00703 suppresses GC cell proliferation and invasion but induces apoptosis and lncRNA GMAN promotes hepatocellular carcinoma progression by interacting with eIF4B." (PMID 34650909, 2021).